ALDH2 (aldehyde dehydrogenase 2 family member)
Diseases named in the same sentence as ALDH2 in open-access papers (continued):
Sharing a sentence is not in itself a finding about the gene and the disease.
alcoholism (continued). "Since acetaldehyde has aversive effects, variants of ADH1B and ALDH2 that increase the levels of acetaldehyde are associated with aversion to alcohol, whereas variants associated with decreased acetaldehyde are associated with increased alcohol consumption and alcohol dependence." (PMID 37792698, 2023). "However, the combination of ADH1B * 1 / * 1 and ALDH2 * 1 / * 2 also has a high risk of alcoholism." (PMID 36028843, 2022). "Thus, use of alcohol flushing data in addition to ALDH2 genotyping is useful to predict, and could be expected to reduce, the risk of future development of alcohol dependence, especially in younger generations." (PMID 34310648, 2021). "In addition, genetic polymorphisms of ALDH2 alter susceptibility to ethanol intake as well as the risk of alcoholism and alcoholic complications, and ALDH2 may possess important therapeutic potential against alcoholism and other forms of myocardial damage." (PMID 30245369, 2018). "Current evidence indicates that ALDH2*2 may influence the risk of alcoholism in Koreans." (PMID 29254215, 2017). "Thus, the influence of ALDH2*2 seems to change over the course of drinking; that is, ALDH2*2 is protective at one stage of alcohol use (i.e., progression to heavy drinking) but becomes a risk factor at another stage (i.e., progression to alcohol-related medical problems)." (PMID 27163368, 2016). "The protective effect of the ADH1B*2 allele against alcoholism vanished in antisocial alcoholics, and the protective effect of the ALDH2*2 allele might disappear in individuals with antisocial personality disorder (ASPD) and carrying the MAOA-uVNTR 4-repeat allele." (PMID 22550993, 2012). "Thus, the ALDH2–2 allele is said to have a protective effect on the risk of alcohol dependence." (PMID 12875047, 2002). "A better understanding of how the interactions of other biological and cultural factors with the ALDH2 genotype help determine the risk of Asians for alcoholism also may have important implications for evaluating the predisposition to alcoholism of other, non-Asian populations." (PMID 31798054, 1995). "Among the identified genes, the ones that stand out are ADH1B and ALDH2, which are included in the metabolism of alcohol and have the greatest impact on the manifestation of alcohol dependence." (PMID 40408386, 2025). "ALDH2 gene is the target of drug for alcoholism which irreversibly inactivate catalytic Cys302 in ALDH2 by carbamylation in the substrate site of the enzyme." (PMID 40436827, 2025). "It is postulated that ALDH2 504lys protects against excessive alcohol use or alcoholism because of unpleasant symptoms secondary to acetaldehyde accumulation." (PMID 39144624, 2024). "Among the currently known genes, ALDH2 and ADH1B had the greatest impact on the risk of alcoholism, which can result in accumulation of acetaldehyde that causes DNA damage and promotes ESCC development." (PMID 37795758, 2023). "Previous studies have revealed protective roles of the ADH1B*2(+) and ALDH2*2(+) genotypes against the development of alcohol dependence." (PMID 35670037, 2023). "ALDH2 rs671 exhibited a protective role in terms of alcohol‐related disorder (OR = 0.04, p = 1.12 × 10−3), alcoholism (OR = 0.05, p = 2.46 × 10−3), and alcoholic liver damage (OR = 0.06, p = 2.86 × 10−3)." (PMID 35670037, 2023). "The safety of paclitaxel for alcohol intolerance has been studied and patients suspected of alcohol intolerance by a screening question were found to carry inactive genotypes of ALDH2 GA (heterozygous ALDH2 *1/*2) or ALDH2 AA (homozygous ALDH2 *2/*2)." (PMID 35657923, 2022). "Knowing an individual’s own ALDH2 plus ADH1B genotype is a growing preventive strategy against alcohol dependence." (PMID 34310648, 2021). "The results indicate that ALDH2*2 plays a major role for acetaldehyde-related physiological negative responses and prove the genetic protection against development of alcoholism in East Asians." (PMID 34439848, 2021).
alcoholism (continued). "Age-adjusted odds ratios (95% confidence intervals) of alcohol dependence according to the combinations of alcohol flushing status and ALDH2 and ADH1B genotypes in the female subjects." (PMID 34310648, 2021). "Age-adjusted odds ratios (95% confidence intervals) of alcohol dependence according to alcohol flushing status and/or the combinations of ALDH2 and ADH1B genotypes in the male subjects." (PMID 34310648, 2021). "Preclinical research also suggested the extraction of Kudzu herbal roots which showed to suppress the alcohol consumption by selective inhibition of the ALDH2 enzyme and indicated the therapeutic effect on alcoholism." (PMID 34439848, 2021). "Age-adjusted odds ratios (95% confidence intervals) of alcohol dependence according to the combinations of alcohol flushing status and ALDH2 and ADH1B genotypes in the male subjects." (PMID 34310648, 2021). "Age-adjusted odds ratios (95% confidence intervals) of alcohol dependence according to alcohol flushing status and/or the combinations of ALDH2 and ADH1B genotypes in the female subjects." (PMID 34310648, 2021). "Commercially available ALDH2 plus ADH1B genotyping has been used as a preventive tool against alcohol dependence in Japan." (PMID 34310648, 2021). "ALDH2 is the key enzyme that metabolizes acetaldehyde and is a great therapeutic target for the treatment of alcoholism." (PMID 32140062, 2020). "Several risk factors for DIULs, including genetic polymorphisms of alcohol and aldehyde dehydrogenases (ADH1B, rs1229984; ALDH2, rs671), have been demonstrated in Japanese alcohol-dependent men." (PMID 30629674, 2019). "Alcoholism was more frequently found in subjects with ALDH2 *1/*1, was significantly lower among those with ALDH2 *1/*2, and no alcoholics were found with the ALDH2 *2/*2, genotype." (PMID 28208752, 2017). "Alcohol flushing and its associated unpleasant feelings due to acetaldehyde accumulation is a strong deterrent against heavy drinking and alcoholism for ALDH2*2 carriers." (PMID 28253921, 2017). "This meta-analysis also examined the effect of ALDH2*2 and ADH1B*2 alleles in combination on the risk for alcohol dependence." (PMID 27163368, 2016). "A similar mechanism of action has been proposed for how ALDH2*2 results in lower rates of alcohol dependence." (PMID 27163368, 2016). "Another study, in contrast, found an interaction between ALDH2*2, ethnicity (i.e. Korean vs. Chinese), and alcohol dependence." (PMID 27163368, 2016). "Because ALDH2*2 has the largest effect on alcohol dependence and because it is found almost exclusively in Asian populations, most of this discussion will focus on this gene and these ethnic groups." (PMID 27163368, 2016). "These analyses found that ALDH2*2 was a significant mediator of protection against alcohol dependence across different ethnic groups." (PMID 27163368, 2016). "Identify and characterize polymorphisms of genes ADH2, ADH3, ALDH2 and CYP2E1 in a Colombian population residing in the city of Bogotá and determine its possible relationship to the alcoholism." (PMID 26848198, 2015). "A dominant-negative ALDH2 SNP, which occurs with an incidence of 35–57% in different East Asian subpopulations, results in markedly reduced alcohol tolerance." (PMID 26491656, 2015). "A number of studies have shown that individuals carrying the ALDH2*2 allele are protected between 66% (heterozygous ALDH2*1/ALDH2*2) and 99% (homozygous ALDH2*2/ALDH2*2) against alcoholism." (PMID 23847486, 2013). "ADH2, ADH3, and ALDH2 are thought to be the pivotal genetic determinants in ethanol metabolism and alcoholism in humans." (PMID 20617031, 2010). "Compared with a Chinese man carrying two active ALDH2*1 alleles and the two copies of the normal ADH1B*1 allele, the odds ratio for risk for alcoholism for a Chinese man carrying one inactive ALDH2*2 allele and two ADH1B*1 alleles is 0.33." (PMID 17718394, 2007).
alcoholism (continued). "Variants of three genes encoding alcohol-metabolizing enzymes, the aldehyde dehydrogenase gene ALDH2 and the alcohol dehydrogenase genes ADH1B and ADH1C, have been associated with reduced rates of alcohol dependence." (PMID 17718397, 2007). "Although this may seem contradictory, individuals with alcohol dependence often carry the high-activity form of ALDH2, which enables the rapid breakdown of acetaldehyde and reduces unpleasant symptoms." (PMID 40943250, 2025). "Increased ALDH2 expression, together with an ADH4 variant with lower binding affinity for alcohol, may represent risk factors for alcoholism in an adult FAS population." (PMID 38886650, 2024). "Noteworthy variants also associated with alcohol dependence and consumption found to be enriched in the cohort included the risk alleles rs1614972 and rs698 in ADH1C, along with rs3762894 and rs671 in ADH4 and ALDH2, respectively." (PMID 38785976, 2024). "Studies have shown that ALDH2 and ADH1B are associated with reduced rates of alcohol dependence." (PMID 37795758, 2023). "However, in a candidate gene study involving ALDH2 and ADH1B in a sample of Japanese individuals with alcohol dependence, ADH1B did associate with flushing." (PMID 37875790, 2023). "ALDH2 is a member of the aldehyde dehydrogenase family; its family member ALDH1 has attracted attention for its role in the treatment of carcinogenesis and cancer, while ALDH2 has been studied for its promotion of alcohol metabolism and protection against alcoholism." (PMID 36865346, 2023). "Our results are consistent with previous studies showing that ALDH2 rs671 polymorphism is associated with the risk of HCC in patients with alcoholism with or without viral hepatitis." (PMID 35877121, 2022). "Also, it is known that there is an inhibitor of ALDH2, disulfiram, which was used as the first-line therapy to treat alcoholism." (PMID 35178443, 2022). "ALDH2, a vital enzyme in alcohol metabolism, is significantly related to alcohol dependence and degenerative diseases, whereas its specific neural molecular mechanism remains unclear." (PMID 36743287, 2022). "ADH1B and ALDH2 may be responsible for alcoholism protection in Asian populations, and the AGO gene cluster is related to RNA interference and silencing." (PMID 35350227, 2022). "Disulfiram represents a potent ALDH1A1 and ALDH2 inhibitor used for the treatment of alcoholism." (PMID 35299840, 2022). "In the past 70 years, disulfiram has been widely used to treat alcoholism for the Caucasian population, almost all having the homozygous ALDH2*1/*1, and the treatment produced strong aversive alcohol reactions and severe cardiovascular side-effects following alcohol consumption." (PMID 34439848, 2021). "Our findings support the use of naltrexone in those patients who might be less susceptible to alcohol dependence (i.e., ADH1C*1 and ALDH2*2), wherein these polymorphisms have been also related to the AUD protection." (PMID 34680127, 2021). "The increased number of ALDH2*1 allele and ADH1B*1 allele in the ALDH2 and ADH1B genotype combinations resulted in the higher risk of alcohol dependence in women as well as men, and similar ORs of alcohol dependence was observed between women and men." (PMID 34310648, 2021). "Despite the low prevalence of alcoholism found in our HCC patients, the data still demonstrated that the wild genotype of ALDH2-“GG” was strongly associated with alcoholism, consistent with our current knowledge regarding ALDH2." (PMID 31737110, 2019). "The low sensitivity in the present study suggests that a lack of alcohol flushing may play a crucial role in the development of alcohol dependence in women with inactive ALDH2." (PMID 30629674, 2019). "However, influenced by social, cultural, and economic factors in the past few decades, such protection against alcohol dependence and alcohol abuse has gradually lost among the large populations of ALDH2*2 carriers." (PMID 28253921, 2017).
alcoholism (continued). "Furthermore, one recent study has reported that rs886205 is associated with altered methylation levels of the negative regulatory promoter fragment and corresponding ALDH2 protein levels in alcohol-dependent patients’ blood during withdrawal." (PMID 28052001, 2017). "In other words, both ALDH2*2 and CD influenced the risk of alcohol dependence, but these effects were independent of each other." (PMID 27163368, 2016). "Other studies, however, have suggested that ASPD might interact with ALDH2*2 to influence alcohol dependence." (PMID 27163368, 2016). "Considering the involvement of dopamine and serotonin in SZ and the comorbidity of SZ with alcohol dependence and cardiovascular diseases, it is plausible that these two genes (ALDH2 and MYL2) may be related to SZ." (PMID 24454952, 2014). "The psychological expectancies of alcoholic drinking are more positive and less negative for ALDH2*1/*2 genotype individuals with alcoholism, although the ALDH2*2 allele has been correlated with negative physiological responses in normal subjects." (PMID 24151617, 2013). "Inhibition of ALDH2 has thus become a possible strategy to treat alcoholism." (PMID 21318009, 2010). "It has been suggested that the mutant ALDH2 gene of ALDH2*2/2 may protect against development of alcohol dependence and alcohol-related disease." (PMID 20617031, 2010). "Second, neither Indo- nor Afro-Trinidadians have the ALDH2*2 allele commonly seen in East Asians that causes flushing following alcohol consumption and protects people from developing alcoholism." (PMID 17718398, 2007). "Perhaps the strongest evidence for GxE interaction effects in alcoholism etiology comes from Japanese researchers who analyzed the effects of the gene that carries the information for aldehyde dehydrogenase 2 (ALDH2), an enzyme that plays a pivotal role in alcohol metabolism in the body." (PMID 12875047, 2002). "The men fell into three groups with respect to their genetic risk for developing alcoholism: extremely low risk (homozygous for the defective ALDH22 allele), moderately low risk (heterozygous for ALDH2), and relatively high risk (homozygous for the functional ALDH21 allele)." (PMID 31798054, 1995). "Because electrophysiological responses appear to be correlated with a person’s genetic predisposition to alcoholism, researchers have used EEG patterns and ERP’s to evaluate alcohol’s effects on brain functioning in college students of Asian origin with different ALDH2 genotypes." (PMID 31798054, 1995). "We hypothesize that this protective effect is not due to a direct role of ALDH2 in insulin function but rather a behavioral consequence, as carriers of the A allele are more likely to abstain from alcohol consumption due to alcohol intolerance." (PMID 40699860, 2025). "ALDH2 rs671 G>A polymorphism reportedly increases gastric cancer susceptibility in alcohol consumers, but the patient in this case study had no history of alcohol abuse." (PMID 35912179, 2022). "However, it may suggest another viewpoint to search the partial protection against alcoholism on the issue of 15% alcohol dependents with heterozygotic ALDH2*1/*2 genotype." (PMID 34439848, 2021). "Rather, the lack of disulfiram effect on ethanol intake in animals fed alcohol chronically (and in alcoholics) may stem from the fact that disulfiram crosses the blood-brain barrier and also inhibits ALDH2 in the brain (Hellström and Tottmar, 1982), increasing acetaldehyde levels in this organ." (PMID 28769774, 2017).
alcoholism (continued). "Finally, genetic factors, such as ALDH2 and their functions, have been largely unstudied in Asian women, and it is thus unclear to what extent biological or cultural differences explain gender differences in alcohol use and alcoholism prevalence among Asians." (PMID 31798054, 1995). "Studies of alcoholics who are heterozygous for the ALDH2 gene may allow researchers to learn more about the interactions among genes or between genes and environmental factors that affect the development of alcoholism." (PMID 31798054, 1995). "However, whether ALDH2 rs671 polymorphism is a risk factor for HCC in patients without alcoholism remains unclear and requires further investigation in a prospective and large cohort study." (PMID 35877121, 2022). "Moreover, the factors associated with mortality included abstinence, ALDH2 rs671 polymorphism, factors related to the severity of cirrhosis, such as Child-Pugh class and serum albumin, and newly developed HCC in patients with cirrhosis with HBV infection and alcoholism." (PMID 35877121, 2022). "Furthermore, astrocytes (a type of glial cell) have acetaldehyde dehydrogenase 2 (ALDH2) which leads to the formation of acetate, which contributes to severe intoxication and alcohol dependence." (PMID 41293241, 2025). "ALDH2 rs671 polymorphism was associated with the risk of HCC and mortality in patients with alcoholism with or without viral hepatitis." (PMID 35877121, 2022). "Never or former flushing markedly increased the ORs of alcohol dependence among carriers of any ALDH2 and ADH1B genotype combination, compared with current flushing." (PMID 34310648, 2021). "Investigation is warranted, in a future study, of whether and how the combination of alcohol flushing status and the ALDH2 plus ADH1B genotype might affect drinking behaviors and manifestations of alcohol-related problems." (PMID 34310648, 2021). "DSF re-purposing from its long-term clinical use against alcoholism to an anti-cancer drug is based on its ability to act as an ALDH1A1/ALDH2 inhibitor, a property not shared by other Cu chelators like TTM." (PMID 30792807, 2019). "A study comparing ALDH2 and ADH1B allele status in Taiwanese with and without ASPD and/or alcohol dependence found that ALDH2*2 showed reduced association with alcohol dependence in people with ASPD compared with people without ASPD." (PMID 27163368, 2016). "It is difficult to transfer this concept to human brain but an analogue of a gene knockout relevant to human alcoholism is the ALDH2 gene (ALDH2-2,2 homozygotes have no ALDH activity)." (PMID 21886551, 2011). "In Asians with no ALDH2*2 alleles, possession of one variant ADH1B*2 allele was associated with a four-fold reduction in alcohol dependence and possession of two ADH1B*2 alleles was associated with a five-fold reduction." (PMID 17718397, 2007). "Thus, ALDH2 rs671 polymorphism is an important factor associated with the risk of HCC and mortality in patients with cirrhosis with alcoholism, with or without HBV infection." (PMID 35877121, 2022). "The temporal profiles of drinking and flushing were evaluated, for the first time, in former flushers with alcohol dependence; these profiles revealed that the flushing tendency disappeared soon after or before the start of habitual drinking, regardless of the ALDH2 genotype." (PMID 34310648, 2021). "Similar to the results from meta- analyses showing that the ALDH2 and ADH1B genes may have an interactive effect on alcohol dependence, some self-report and alcohol-challenge data in Asians suggest that the effects of ADH1B*2 may be stronger in individuals with ALDH2*1/*2 genotype." (PMID 27163368, 2016). "Furthermore, although ALDH2*2 protects against the development of alcohol dependence, the protection is not complete." (PMID 27163368, 2016).